LECT2 (leukocyte cell derived chemotaxin 2)
Diseases named in the same sentence as LECT2 in open-access papers (continued):
Sharing a sentence is not in itself a finding about the gene and the disease.
Insulin resistance (continued). "We investigated the state of insulin resistance and serum LECT2 concentrations in SAMP8 mice." (PMID 29630667, 2018). "In these mice, serum concentrations of leukocyte cell–derived chemotaxin 2 (LECT2), which is known to induce insulin resistance in skeletal muscle, were elevated, and insulin signaling in muscle, as determined by the phosphorylation levels of Akt and p70 S6 kinases, tended to be decreased." (PMID 29630667, 2018). "GTEs also reduced serum LECT2 concentrations, which were correlated with insulin resistance." (PMID 29630667, 2018). "In humans, serum LECT2 concentrations correlated positively with insulin resistance." (PMID 30374329, 2018). "Indeed, deletion of Lect2 in mice improved high fat diet-induced insulin resistance with decreased c-jun N-terminal kinase signaling in skeletal muscle." (PMID 30374329, 2018). "Furthermore, Lect2 deletion attenuated skeletal muscle insulin resistance in mice fed a high-fat diet via dephosphorylation of the Jun NH2-terminal kinase." (PMID 28278265, 2017). "Furthermore, we examined the relationship of LECT2 levels with the presence of metabolic syndrome, hypertension, insulin resistance and dyslipidemia to determine the clinical significance of measuring circulating LECT2." (PMID 28278265, 2017). "Furthermore, we examined the relationship of LECT2 levels with the presence of metabolic syndrome, hypertension, insulin resistance and dyslipidemia to demonstrate the clinical significance of measuring circulating LECT2." (PMID 28278265, 2017). "The present study also showed that blood lipids such as triglycerides and LDL cholesterol levels were independently associated with LECT2, suggesting that LECT2 plays a role in the development of dyslipidemia rather than insulin resistance in male participants." (PMID 28278265, 2017). "Among these hepatokines are fetuin A, follistatin, HFREP1, LECT2, PEDF, and ectodysplasin, collectively exacerbating insulin resistance in skeletal muscle and adipose tissue through the activation of the c-Jun N-terminal kinase signaling pathway." (PMID 40704318, 2025). "For example, LECT2 serum levels are rapidly increased prior to body weight gain and exhibit a positive correlation with the extent of NAFLD, insulin resistance, hepatic inflammation, and liver fibrosis." (PMID 34944728, 2021). "Hepatokines, including leukocyte cell-derived chemotaxin 2 (LECT2) and hepassocin (HSP), can contribute to the development of LSMI by increasing insulin resistance." (PMID 33562473, 2021). "Therefore, LECT2 may influence insulin resistance specifically in women." (PMID 28278265, 2017). "Recently, we reported that a dipeptidyl peptidase 4 inhibitor improves hepatic steatosis as well as insulin resistance through AMP-activated protein kinase (AMPK)- and JNK-dependent inhibition of LECT2 expression." (PMID 28376109, 2017). "In line with this notion, LECT2-deficient mice fed an HFD exhibited improved insulin sensitivity in skeletal muscle, as opposed to the mice administered recombinant LECT2 protein, which developed insulin resistance in skeletal muscle." (PMID 34944728, 2021). "Although we have no direct evidence for the effect of serum LECT2 on muscle weight, insulin resistance assessed as HOMA-IR had an intervention effect of serum LECT2 on muscle weight." (PMID 29630667, 2018). "Previously, we demonstrated that LECT2 increased mammalian target of rapamycin (mTOR) phosphorylation, sterol regulatory element-binding protein (SREBP)-1 cleavage, lipid accumulation, and insulin resistance in HepG2 cells." (PMID 28376109, 2017). "Plasma LECT2 levels differed based on the presence of metabolic syndrome and dyslipidemia, but not hypertension and insulin resistance." (PMID 28278265, 2017). "However, high levels of LECT2 in the bloodstream of obese individuals might continuously bind to the receptors, resulting in JNK phosphorylation, thereby potentially contributing to insulin resistance." (PMID 32764719, 2020).
Insulin resistance (continued). "Although LECT2 levels were not different between the presence and absence of insulin resistance, fasting insulin level (r = 0.24, P = 0.004) and HOMA-IR (r = 0.22, P = 0.010) were significantly correlated with LECT2 levels." (PMID 28278265, 2017).
liver fibrosis (21 papers, 2020 to 2025). "Leukocyte cell-derived chemotaxin 2 (LECT2) was proposed as the key gene associated with hepatic fibrosis in BA, but the molecular mechanism is unclear." (PMID 35928681, 2022). "Further ELISA testing revealed that serum LECT2 levels were also consistent with these results, suggesting that LECT2 is an important factor associated with liver fibrosis in BA." (PMID 35928681, 2022). "The expression of LECT2 in serum, protein and mRNA of the human liver tissues was detected to analyze the possible associations between LECT2 and liver fibrosis." (PMID 34631799, 2021). "In conclusion, LECT2 is a novel and direct predictor, which is suitable as a screening biomarker for significant and advanced liver fibrosis, and the diagnostic efficacy of LECT2 in different situations of patients with CHB had been confirmed." (PMID 34631799, 2021). "This is the first report that aimed to figure out the association between the expression of LECT2 and the severity of liver fibrosis." (PMID 34631799, 2021). "In this study, we analyzed the gene expression profile of patients with BA by WGCNA algorithm and screened that the key genes associated with hepatic fibrosis in biliary atresia is LECT2 (Leukocyte Cell Derived Chemotaxin 2)." (PMID 34899846, 2021). "Meanwhile, TGF-β1 is secreted by macrophages to regulate LECT2 associated with BA liver fibrosis." (PMID 35928681, 2022). "Thus, LECT2 may be used as a noninvasive diagnostic marker and potential therapeutic target for liver fibrosis." (PMID 35656863, 2022). "Consequently, our group aimed to detect whether the expression of LECT2 was associated with liver fibrosis in CHB patients and confirm the effectiveness of LCET2 for predicting liver fibrosis." (PMID 34631799, 2021). "The newly described Tie1 ligand leukocyte cell‐derived chemotaxin 2 (LECT2) has been implicated in liver fibrosis where LECT2 binding to Tie1 results in dephosphorylation of Tie1, disruption of Tie1/Tie2 heterodimers, and promotion of Tie2/Tie2 homodimers, leading to enhanced liver fibrosis." (PMID 32406209, 2020). "LECT2 expression in serum and liver macrophages was associated with increased TGF-beta 1 secretion by liver CD163 (+) M2 macrophages and liver fibrosis." (PMID 40270513, 2025). "Research has shown that LECT2 holds significant potential for the treatment of immune diseases, liver fibrosis, liver cancer, amyloidosis, and other illnesses." (PMID 38881894, 2024). "BA is the fifth research hotspot to study the mechanism of LECT2-induced liver fibrosis in patients with Biliary Atresia." (PMID 38881894, 2024). "Knockdown of the LECT2 gene significantly promotes portal vein angiogenesis and sinusoidal capillary reduction, which alleviates the symptoms of liver fibrosis." (PMID 38881894, 2024). "Overexpression of LECT2 leads to the deterioration of liver fibrosis by inhibiting portal vein angiogenesis and promoting sinus capillary formation." (PMID 38881894, 2024). "Numerous studies have demonstrated the involvement of LECT2 in various liver conditions, including hepatitis, acute liver failure, liver fibrosis, nonalcoholic fatty liver disease, cirrhosis, and HCC." (PMID 38881894, 2024). "Meng Xu found that direct binding of LECT2 to Tie1 can inhibit portal vein angiogenesis, induce hepatic sinusoidal capillarization, and promote liver fibrosis." (PMID 37153080, 2023). "LECT2 over‐expression inhibited portal angiogenesis, promoted liver sinusoid capillarization and worsened the liver fibrosis in vivo." (PMID 35656863, 2022). "Both IHC and qPCR results confirmed that the expression of LECT2 was significantly elevated in BA liver tissues, and its expression was positively correlated with the degree of liver fibrosis." (PMID 35928681, 2022). "Xu et al18 found that there was a positive relationship between LECT2 and the progression of liver fibrosis." (PMID 35656863, 2022).
liver fibrosis (continued). "LECT2‐Tie1 signal promoted liver sinusoid capillarization and inhibited portal angiogenesis, thereby worsening the liver fibrosis." (PMID 35656863, 2022). "In this study, LECT2 was initially distributed scattered in the portal area and gradually spread to the whole hepatic lobule with the aggravation of liver fibrosis, which possibly resulted from its function as a leukocyte cell-derived chemotaxin." (PMID 35928681, 2022). "As a functional ligand of endothelial cell-specific receptor Tie1, LECT2 promotes liver fibrosis by inhibiting portal angiogenesis and promoting capillarization of liver sinusoids in various liver fibrosis models." (PMID 35837401, 2022). "Xu et al16 discovered that a higher level of serum LECT2 was present in patients with liver fibrosis, which was closely correlated with liver fibrosis staging." (PMID 35656863, 2022). "Higher expressions of serum LECT2 were detected in patients with liver fibrosis, and they were closely correlated with liver fibrosis staging, even if these patients were within normal serum ALT levels." (PMID 35656863, 2022). "This study aimed to explore the expression of LECT2 and its relationship with the inflammatory response in the procession of BA liver fibrosis." (PMID 35928681, 2022). "The overexpression of LECT2 inhibits portal angiogenesis and promotes sinusoid capillarization, leading to a worsening of hepatic fibrosis." (PMID 36010588, 2022). "In contrast, significantly stronger LECT2 expression was observed in the liver tissues with significant (≥S2) and advanced (≥S3) liver fibrosis." (PMID 34631799, 2021). "Leukocyte cell-derived chemotaxin-2 (LECT2) has been shown to contribute to liver fibrosis progression." (PMID 34631799, 2021). "It is obvious that with the aggravation of liver fibrosis, the number of LECT2+ cells increased gradually." (PMID 34631799, 2021). "Our previous study reported the phenomenon that LECT2 played an important role in promoting the aggravation of liver fibrosis, and liver cirrhosis patients showed more concentration of LECT2 in the serum." (PMID 34631799, 2021). "And the LECT2 was shown to be more positively correlated with the stages of liver fibrosis than the others (r = 0.673, 0.423, 0.450 for LECT2, APRI, FIB-4, respectively)." (PMID 34631799, 2021). "The data showed that there was a positive relationship between LECT2 and the progression of liver fibrosis." (PMID 34631799, 2021). "The expression of LECT2 mRNA was compared between the <S2 group and the ≥S2 group, data showed that it was significantly higher in the ≥S2 (significant liver fibrosis) group (p < 0.01)." (PMID 34631799, 2021). "Leukocyte cell-derived chemotaxin 2 (LECT2), a functional ligand of Tie1 expressed by hepatocytes and endothelial cells, promotes the capillarization of LSECs in the liver fibrosis rodent model." (PMID 33935770, 2021). "The concentration of LECT2 mRNA in the ≥S3 (advanced liver fibrosis) group was more (p < 0.01) than that in the <S2 group." (PMID 34631799, 2021). "More importantly, our previous studies confirmed for the first time that LECT2 can bind to Tie1 as a ligand to promote the progress of liver fibrosis by affecting angiogenesis, and verified the conclusion in vitro and experimental animal models." (PMID 34631799, 2021). "To verify that LECT2 is a direct predictor of liver fibrosis, we not only detected serum LECT2 but also examined the protein levels of LECT2 in the liver tissues." (PMID 34631799, 2021). "Our data showed that there was an obvious correlation between the high expression of serum LECT2 and the deterioration of liver fibrosis." (PMID 34631799, 2021). "In the process of studying the mechanism of LECT2 promoting liver fibrosis, we found that serum LECT2 was raised significantly in patients with liver cirrhosis and was increased as the Child-Pugh score progressed from A to D." (PMID 34631799, 2021).
liver fibrosis (continued). "The optimal cutoff value of LECT2 is 4.13 ng/ml to predict significant liver fibrosis (≥S2), 6.10 ng/ml to predict advanced liver fibrosis (≥S3)." (PMID 34631799, 2021). "Data showed that LECT2 was the independent predictor of significant liver fibrosis (OR = 2.311, P = 0.000) and advanced liver fibrosis (OR = 1.555, P = 0.000)." (PMID 34631799, 2021). "Moreover, LECT2 is also considered a pivotal gene in BA liver fibrosis to boost fibrosis by triggering fibrous genes such as α-smooth muscle actin and collagen type I alpha 1 Chain." (PMID 38881894, 2024). "In brief, the referred researches illustrate that LECT2 may play a crucial role in liver fibrogenesis, and it may represent a potential biomarker and therapeutic target for liver fibrosis." (PMID 35656863, 2022). "In addition, the combination of leukocyte cell-derived chemokine 2 (LECT2) produced by HCs and Tie1 expressed by LSECs also participates in the progress of liver fibrosis." (PMID 35837401, 2022). "The expressions of serum LECT2 may vary in different pathogenesis, with the advancement of liver fibrosis." (PMID 35656863, 2022). "Interestingly, the hepatic fibrosis changes were reversed in LECT2-KO mice, suggesting the LECT2-Tie1 signaling pathway as a potential target for liver fibrosis treatment." (PMID 36010588, 2022). "So, in what way does LECT2 interact with CD163+ macrophages in the process of BA liver fibrosis?" (PMID 35928681, 2022). "After demonstrating the relationship between LECT2 and BA liver fibrosis, we further investigated whether LECT2 is involved in the inflammatory response to influence the liver fibrosis process." (PMID 35928681, 2022). "The hub gene screened by PPI network was LECT2, which may be a key gene in the development of biliary atresia liver fibrosis." (PMID 34899846, 2021). "The serum level of LECT2 was upregulated in various liver fibrosis groups, suggesting the possibility that LECT2 could discriminate the liver fibrosis stage." (PMID 34631799, 2021). "All the results confirmed that LECT2 could act as a perfect predictor and thus offers a novel and direct biomarker to estimate liver fibrosis more accurately." (PMID 34631799, 2021). "The number of LECT2+ cells in different liver fibrosis stages was calculated." (PMID 34631799, 2021). "Whether AB‐Tie1‐39 can block LECT2‐Tie1 binding or could be used as a therapy in liver fibrosis or indeed atherosclerosis may be interesting avenues of investigation." (PMID 32406209, 2020). "Furthermore, given that the role of LECT2 may be influenced by the extent of liver fibrosis, additional stratified analyses based on the fibrosis severity are warranted to gain deeper insights into its impact." (PMID 40284206, 2025). "On the other hand, adeno-associated virus vector serotype 9 carrying LECT2 short hairpin RNA (AAV9-LECT2-shRNA) can target mouse LECT2 to inhibit LECT2/Tie1 signaling, thereby inducing portal angiogenesis, suppressing hepatic sinusoidal capillarization, and alleviating liver fibrosis." (PMID 37153080, 2023). "LECT2 could act as a direct biomarker to predict liver fibrosis more accurately." (PMID 35656863, 2022). "LECT2 may be a potential biomarker and therapeutic target for liver fibrosis." (PMID 35656863, 2022). "However, whether LECT2 can be used as a direct biomarker to diagnose the early stage of liver fibrosis in CHB patients remains unknown." (PMID 34631799, 2021). "The results showed that LECT2 was regulated by β-catenin/TCF4 signaling, thereby regulating angiogenesis and participating in liver fibrosis." (PMID 38881894, 2024). "Some vivo studies indicate that high expression of LECT2 in HCC cells can promote sinusoid capillarization, inhibit portal angiogenesis, and promote liver fibrosis." (PMID 36776357, 2022).
liver fibrosis (continued). "The beneficial effects of hepatokines include 1) improvement of insulin sensitivity (FGF21); 2) prevention of liver fibrosis (FGF21, HMGB1, PST, AHSG and SERPINF1) and 3) reduction of inflammation and lipid accumulation (FGF21, HMGB1 and LECT2)." (PMID 36267567, 2022). "The results revealed that LECT2 and CD163 + macrophages have a mutually promoting role in BA liver fibrosis." (PMID 35928681, 2022). "Our results showed that the LECT2 protein levels and mRNA levels of LECT2 in hepatic tissue were upregulated in CHB patients who were diagnosed with significant and advanced liver fibrosis by liver biopsy." (PMID 34631799, 2021). "However, no one had analyzed the association between LECT2 and liver fibrosis in CHB patients." (PMID 34631799, 2021). "On the other hand, LECT2 levels do not correctly reflect the inflammatory change and liver fibrosis required for the diagnosis of NASH." (PMID 37957316, 2024). "CHM2 suppresses angiogenesis by blocking VEGF165-VEGFR2 signaling in liver cancer and reduces endothelial cell migration and tube formations by activating LECT2-Tie1 signaling in liver fibrosis." (PMID 36969200, 2023). "It is obvious that whether in the training group or the validation group, the level of serum LECT2, APRI, and FIB-4 increased with the aggravation of liver fibrosis (all p < 0.05), and the patients with S4 showed the highest LECT2." (PMID 34631799, 2021). "Except direct liver injury and subsequent development and progression of liver fibrosis, several hepatokines (e.g., fetuin A and B, selenoprotein P, fibroblast growth factor 21 (FGF12), leukocyte cell-derived chemotaxin 2 (LECT2), and hepassocin (HPS)) are produced." (PMID 33204675, 2020). "No research has focused on the role of LECT2 in liver fibrosis in CHB patients." (PMID 34631799, 2021). "LECT2, a chemotactic factor produced by tissue cells in response to external stimulation, plays an important role in cellular signaling pathways and is a key site in the complex regulation network of liver fibrosis, but no study has reported the prognosis value of LECT2 in biliary atresia." (PMID 34899846, 2021).